SIGMAR1 (sigma non-opioid intracellular receptor 1)
Diseases named in the same sentence as SIGMAR1 in open-access papers (continued):
Sharing a sentence is not in itself a finding about the gene and the disease.
cardiac hypertrophy (8 papers, 2019 to 2025). "Sigmar1 global knockout (Sigmar1−/−) mice showed cardiac hypertrophy, contractile dysfunction, perivascular and interstitial fibrosis in the heart, and a decline in mitochondrial respiratory function." (PMID 38742156, 2024). "WGA staining revealed a significant increase in the cross-sectional area of the ventricular myocardium in ISO-treated mice, and Sigmar1 knockout aggravated the myocardial hypertrophy." (PMID 37720144, 2023). "A number of studies have shown that stimulation of Sigmar1 using its agonists (e.g., dehydroepiandrosterone and fluvoxamine) elicit protective effects against PO-induced cardiac hypertrophy in ovariectomized rats and TAC-induced cardiac hypertrophy in mice." (PMID 34305655, 2021). "The Sigmar1 agonist SA4503 can improve cardiac hypertrophy and dysfunction in mice with HF." (PMID 37720144, 2023). "In addition, several studies also demonstrated Sigmar1’s cardioprotective roles in animal models of cardiac hypertrophy and heart failure." (PMID 37051024, 2023). "Moreover, cardiac hypertrophy in mice induced by aortic banding also exhibit reduced expression levels of Sigmar1 protein in the brain and depression-like behavior, along with the development of impaired cardiac function." (PMID 34305655, 2021). "Several studies have demonstrated that the neurosteroid dehydroepiandrosterone (DHEA) serves as an endogenous ligand for Sigmar1, and DHEA treatment ameliorated PO-induced cardiac hypertrophy in ovariectomized rats." (PMID 34305655, 2021). "It has also been shown that treatment with non-selective Sigmar1 agonist improved cardiac contractile dysfunction and cardiac hypertrophy by activating Akt-eNOS signaling axis in pressure-overload-induced cardiac injury model of rat and mice." (PMID 37051024, 2023).
diabetes (7 papers, 2017 to 2024). "Additionally, IQGAP1 localizes to the same subcellular regions as SigmaR1, including the plasma membrane, the nuclear envelope and the ER, and is involved in similar disease outcomes such as cancer and diabetes." (PMID 37444574, 2023). "However, the molecular role for Sigmar1 in the postnatal development of the rat kidneys and in distal tubular damage in the pathogenesis of diabetes requires further investigation." (PMID 34305655, 2021). "The protective effect of Sigmar1 in diabetes-induced retinal neurodegeneration has also been demonstrated using Sigmar1 null mice, where the absence of Sigmar1 aggravated retinal ganglionic cell dysfunction in streptozotocin-injected diabetic mice." (PMID 34305655, 2021).
frontotemporal lobar degeneration (7 papers, 2015 to 2022). "Heterozygous 3′-UTR variants in SIGMAR1 have been also identified in individuals with frontotemporal lobar degeneration–motor neuron disease but their pathogenic role is still unclear." (PMID 27629094, 2016). "Furthermore, variants in the 3′-untranslated region (UTR) of the SIGMAR1 gene were reported in patients with frontotemporal lobar degeneration (FTLD) or motor neuron disease with FTLD." (PMID 26213621, 2015). "The association of Sig-1R and TDP-43 was documented in a study in which a nonpolymorphic mutation in the 3′-untranslated region of SIGMAR1 was identified in patients from the frontotemporal lobar degeneration-motor neuron disease (FTLD-MND) pedigree." (PMID 28917260, 2017).
heart failure (7 papers, 2021 to 2024). Inability of the heart to pump blood at an adequate rate to meet tissue metabolic requirements. "Consequently, we propose that both the bile secretion pathway (particularly the role of taurocholic acid) and the tryptophan metabolism pathway are implicated in how Sigmar1 knockout affects the progression of heart failure." (PMID 37720144, 2023). "In murine models, agonistic stimulation of Sigmar1 decreases cardiac fibroblast activation and fibrosis induced by pressure overload, heart failure, pulmonary arterial hypertension, and ventricular arrhythmias." (PMID 39200372, 2024). "Therefore, achieving an understanding of the molecular function of Sigmar1 would allow us to design selective Sigmar1 activators, which could be used to therapeutically to prevent cardiomyocytes loss and mitigate the clinical progression of heart failure in patients." (PMID 34305655, 2021).
schizophrenia (7 papers, 2014 to 2025). A major psychotic disorder characterized by abnormalities in the perception or expression of reality. "Furthermore, sigma non-opioid intracellular receptor 1 (SIGMAR1) gene polymorphism is involved in the pathogenesis of schizophrenia." (PMID 36778640, 2023). "People with schizophrenia who are Pro carriers for SIGMAR1 gene have significantly lower activation of the right pre-frontal cortex during the VFT as compared to healthy people who are homozygous for the Gln/Gln genotype." (PMID 36778640, 2023).
Anxiety (6 papers, 2021 to 2025). Intense feelings of nervousness, tension, or panic often arise in response to interpersonal stresses. "It has been shown that Sigmar1−/− mice exhibit an anxiety-like phenotype of behavior in the open field test (OF) and the elevated plus maze test (EPM)." (PMID 34064275, 2021). "Studies also demonstrated the development of a depressive-like phenotype and a gender-related anxiety, depressive-like and memory related alterations in the Sigmar1–/– mouse." (PMID 34305655, 2021). "The negative influence of Sigma1R antagonists on the anxiolytic-like effect of benzodiazepines is consistent with the anxiety-like behavior of Sigmar1−/− mice in standard tests." (PMID 37298532, 2023). "Additionally, a lack of Sigmar1 showed normal anxiety-like behavior as shown during the elevated plus maze test and light-dark transfer test." (PMID 34305655, 2021).
colorectal cancer (6 papers, 2021 to 2025). A primary or metastatic malignant neoplasm that affects the colon or rectum. "A direct interaction has also demonstrated between the Sigmar1 and human Ether-à-go-go-Related Gene (hERG) that promotes hERG protein level in n myeloid leukemia and colorectal cancer cells." (PMID 34305655, 2021). "Patients with colorectal cancer also exhibit upregulated levels of Sigmar1 depending on the stage of the disease, especially in the upper colon." (PMID 34305655, 2021).
juvenile amyotrophic lateral sclerosis (6 papers, 2013 to 2025). Juvenile amyotrophic lateral sclerosis (JALS) is a very rare severe motor neuron disease characterized by progressive upper and lower motor neuron degeneration causing facial spasticity, dysarthria, and gait disorders with onset before 25 years of age. "We present the case of a 16-year-old East Asian Chinese girl with a novel mutation in the SIGMAR1 gene, initially diagnosed as juvenile amyotrophic lateral sclerosis (JALS)." (PMID 40309037, 2025). "Mutations in SIGMAR1 gene cause juvenile amyotrophic lateral sclerosis 16 with autosomal recessive inheritance pattern." (PMID 33123684, 2020). "Other variants in this class include SIGMAR1:NM_005866.2:c.73delG;p.(Val25Serfs∗18), which supports the involvement of this gene in autosomal recessive juvenile amyotrophic lateral sclerosis." (PMID 33456446, 2020).
neuroblastoma (6 papers, 2014 to 2025). Neuroblastoma (NB) is the most common solid, extracranial childhood tumor. "The presence of the c.672∗26C > T, c.672∗47G > A, and c.672∗51G > T mutations within the 3′−UTR of SIGMAR1 affect transcript stability resulting in increased Sigmar1 transcript in human neuroblastoma SK−N−MC and HEK-293 cells." (PMID 34305655, 2021). "Sigmar1 inhibition by antagonists also showed to decrease in calcium response in neuroblastoma cells." (PMID 34305655, 2021). "ER-stress (induced by tunicamycin or thapsigargin) transcriptionally increased Sigmar1 protein levels via the PERK/eIF2α/ATF4 pathway and ameliorated cell death signaling under in HEK293 cells or mouse neuroblastoma (Neuro2a) cells." (PMID 34305655, 2021). "The molecular role played by Sigmar1 in regulating mitochondrial calcium signaling has been reported by studies showing that Sigmar1 interacts with IP3R3 to regulate ER-mitochondrial calcium levels under ER-stress conditions in CHO and neuroblastoma cells." (PMID 34305655, 2021).
prostate carcinoma (6 papers, 2003 to 2024). A carcinoma that arises from epithelial cells of the prostate gland. "Here, we show that Sigma1/SIGMAR1, a unique ligand-operated scaffolding protein, regulates LD metabolism in prostate cancer cells." (PMID 37874216, 2023). "Inhibition of Sigmar1 by ligands limited the translocation of androgen receptor and mediated protective effects in prostate cancer cells." (PMID 34305655, 2021). "On the other hand, our data were consistent with those of a previous study which revealed that the SIGMAR1 inhibitor decreased cell surface PD-L1 expression and suppressed the functional interaction of PD-1 and PD-L1 in a coculture of T cells and breast and prostate cancer cells." (PMID 39595926, 2024).
Sepsis (6 papers, 2021 to 2025). Sepsis is defined as life-threatening organ dysfunction caused by a dysregulated host response to infection. "During sepsis, Sigmar1 has been shown to interact with IRE1, reducing the splicing of XBP1, resulting in reduced production of inflammatory cytokines and increasing the longevity of mice in sub-lethal models of sepsis." (PMID 34305655, 2021). "Among that, Lrp5, Cyp7a1, Nfkbiz, Sigmar1, Fabp7, and Hao1 have been reported in the inflammatory response and lipid metabolic process, suggesting that these genes may play an important role in modulating sepsis-induced system inflammation in WT and LBP-deficient rats after LPS injection." (PMID 35005033, 2021).
cardiomyopathy (5 papers, 2020 to 2024). A disease of the heart muscle or myocardium proper. "Here we show that Sigmar1 is a therapeutic target for methamphetamine-associated cardiomyopathy and defined the molecular mechanisms using autopsy samples of human hearts, and a mouse model of “binge and crash” methamphetamine administration." (PMID 33203971, 2020). "Therefore, Sigmar1 is a viable therapeutic agent for protection against methamphetamine-associated cardiomyopathy." (PMID 33203971, 2020). "We used multi-omics analysis to examine the effects of Sigmar1 on ISO-induced TTS-like cardiomyopathy in mice." (PMID 37893138, 2023). "In this study, we used a multi-omics approach to investigate the role of Sigmar1 in an isoprenaline hydrochloride (ISO)-induced TTS-like cardiomyopathy mouse model." (PMID 37893138, 2023). "We recently reported a potential protective role for Sigmar1 in methamphetamine-induced cardiomyopathy, where methamphetamine reduced Sigmar1 protein levels in mice, rats, and humans." (PMID 34305655, 2021). "We demonstrated a novel correlation among Sigmar1 level, Sigmar1-dependent regulation of the CREB-Fis1 signaling axis, and mitochondrial dysfunction contributing to the development of METH-associated cardiomyopathy." (PMID 33203971, 2020). "Our results contrast with findings in human hearts of methamphetamine users that develop cardiomyopathy in which Sigmar1 levels are significantly decreased and in chronic heart failure models that found a reduction in Sigmar1 cardiac expression in rats with left anterior descending artery ligation." (PMID 39200372, 2024). "Hence, METH-induced decreased Sigmar1 expression underlies the alteration in CREB/pCEBSer133/Fis1 signaling that adversely affects mitochondrial dynamics, morphometry, and respiration in cardiomyocytes, providing evidence for a pathogenic molecular mechanism in METH-induced cardiomyopathy." (PMID 33203971, 2020).
epilepsy (5 papers, 2020 to 2025). A brain disorder characterized by episodes of abnormally increased neuronal discharge resulting in transient episodes of sensory or motor neurological dysfunction, or psychic dysfunction. "MR analysis identified 14 drug target genes causally associated with epilepsy or its subtypes and identified MCHR1 and SIGMAR1 as drug target genes of interest for future studies in epilepsy." (PMID 40170563, 2025).
ischemia (5 papers, 2016 to 2025). A hypoperfusion of the BLOOD through an organ or tissue caused by a PATHOLOGIC CONSTRICTION or obstruction of its BLOOD VESSELS, or an absence of BLOOD CIRCULATION. "A recent study showed that the opioid receptor agonist, oxycodone, preserves cardiac microvascular endothelial cell integrity and myocardial function after ischemia-reperfusion injury by binding to Sigmar1." (PMID 38742156, 2024). "FMD measurements showed that transient hindlimb ischemia for 1 min with an occlusion cuff in Sigmar1−/− mice did not induce femoral artery vasodilation upon reperfusion." (PMID 38742156, 2024).
retinal degeneration (5 papers, 2011 to 2022). Degeneration of the retina. "Our data indicated faster retinal ganglion cell death in Sigmar1−/− than in wild-type mice under the stresses caused by optic nerve crush, providing direct evidence for a role of the σR1 in alleviating retinal degeneration." (PMID 21541278, 2011). "7kCHOL treatment robustly decreased expression of Sigmar1, whose corresponding protein has neuroprotective properties that have been documented in animal models of retinal degenerations; Sigmar1 knockdown increases CHOP expression and exacerbates ER stress." (PMID 33652836, 2021).
juvenile ALS (4 papers, 2016 to 2025). "Two heterozygous variants were detected in genes associated with autosomal dominant spinal muscular atrophy and CMT2 (BICD2 and TRPV4) and one homozygous variant was detected in SIGMAR1, a gene associated with autosomal recessive dHMN and juvenile ALS." (PMID 27629094, 2016). "Causal mutations in proteins such as SIGMAR1 or VABP, both ER membrane-expressed proteins involved in MAM formation, have been identified in familial cases of juvenile ALS." (PMID 38170217, 2024). "Mutations in sigma nonopioid intracellular receptor 1 (SIGMAR1), which encodes the sigma-1 receptor (Sig1R), cause juvenile ALS (ALS16), and mutant Sig1R loses its MAM-specific chaperone protein function." (PMID 37408276, 2023).
myocardial infarction (4 papers, 2021 to 2024). Gross necrosis of the myocardium, as a result of interruption of the blood supply to the area, as in coronary thrombosis. "Particularly, chronic SIGMAR1 activation can improve the ventricular remodeling after myocardial infarction in rats and decrease the susceptibility to ventricular arrhythmia, suggesting that SIGMAR1 might help to alleviate myocardial I/R injury." (PMID 35412431, 2022). "However, a recent study showed that chronic Sigmar1 activation ameliorated ventricular remodeling and decreased susceptibility to ventricular arrhythmias after myocardial infarction in rats." (PMID 34305655, 2021). "Importantly, compelling evidence indicates that chronic SIGMAR1 activation can improve the ventricular remodeling after myocardial infarction in rats and decrease the susceptibility to ventricular arrhythmia, suggesting that SIGMAR1 might relieve myocardial I/R injury." (PMID 35412431, 2022).
neuropathy (4 papers, 2020 to 2025). A disorder affecting the nervous system that manifests with pain, tingling, numbness, and/or muscle weakness. "The homozygous c.151+1G>T mutation in SIGMAR1 (F7) was associated with progressive neuropathy and pyramidal signs." (PMID 33381078, 2020).
cognitive decline (3 papers, 2019 to 2021). "Sigmar1 is also involved in both the chronic effects and withdrawal effects of alcohol consumption, where modulation of Sigmar1 using a selective agonist reduced hyper-responsiveness and mitigate the effects of chronic alcohol consumption induced cognitive decline." (PMID 34305655, 2021). "Adult onset SIGMAR1-ALS can be associated with FTD, though cognitive decline is not observed in SIGMAR1-JALS." (PMID 34946884, 2021).
hepatocellular carcinoma (3 papers, 2020 to 2024). A malignant tumor that arises from hepatocytes. "The inhibition of SigmaR1 in these cell lines resulted in increased cellular death by sorafenib-induced ferroptosis both in vitro and in vivo, suggesting that SigmaR1 shields hepatocellular carcinoma cells against sorafenib-induced apoptosis." (PMID 37444574, 2023). "Interestingly, our results were consistent with those of an earlier study that also observed that SIGMAR1 silencing increased the sorafenib sensitivity of hepatocellular carcinoma cells in vitro and in vivo." (PMID 39595926, 2024). "SigmaR1 regulates reactive oxygen species (ROS) via the ferroptosis component nuclear-erythroid 2-related factor 2 (NRF2) and was found to be both up-regulated and translocated away from the nucleus in hepatocellular carcinoma cell lines in response to the ferroptosis inducer sorafenib." (PMID 37444574, 2023).
lung carcinoma (3 papers, 2018 to 2023). "Studies suggested Sigmar1 as a potential biomarker for lung cancer diagnosis and therapeutic targets as Sigmar1 levels were elevated in lung cancer in animal models as well as in tumor cell lines." (PMID 37051024, 2023).
Ventricular arrhythmia (3 papers, 2021 to 2024). "Sigmar1 activation following treatment with fluvoxamine improved cardiac function through reduced susceptibility to ventricular arrhythmias, mitigated myocardial fibrosis, lightened sympathetic remodeling and electrical remodeling, and upregulated Sigmar1 protein levels." (PMID 34305655, 2021).
alcohol dependence (2 papers, 2014 to 2019). Physical and psychological dependence on alcohol. "A single human study has so far shown a possible role for Sig-1R in AUD, specifically that a Japanese population of alcoholic subjects display three polymorphisms in the 5’ untranslated region of the gene coding Sig-1Rs (SIGMAR1) that are highly associated with alcoholism." (PMID 31258483, 2019).
atrial fibrillation (2 papers, 2019 to 2021). A disorder characterized by an electrocardiographic finding of a supraventricular arrhythmia characterized by the replacement of consistent P waves by rapid oscillations or fibrillatory waves that vary in size, shape and timing and are accompanied by an irregular ventricular response. "Stimulation of Sigmar1 has also been shown to exhibit cardioprotection in tachycardia, atrial fibrillation, and asphyxia cardiac arrest." (PMID 34305655, 2021). "Similar to the effects of Sigmar1 in ventricles, inhibition of Sigmar1 by treatment with antagonists altered atrial electrophysiology, reducing effective refractory period, action potential duration, and leading to increased inducibility and time of atrial fibrillation." (PMID 34305655, 2021).
colon cancer (2 papers, 2020 to 2022). "In support, downregulation of SigmaR1 or the application of an inhibitory SigmaR1 ligand igmesine in breast and colon cancer cells has abolished the interplay of SK3 with Orai1 channels in lipid rafts and decreased their levels in lipid nanodomains." (PMID 33333945, 2020). "While SigmaR1 and STIM1 interact directly in HEK 293 cells, in breast and colon cancer cells, this receptor associates directly with SK3 and triggers a close association of Orai1 and SK3." (PMID 33333945, 2020). "In contrast, SigmaR1 was directly bound to SK3 in breast and colon cancer cells and supported the interplay of SK3 and Orai1." (PMID 35327543, 2022). "In fact, knockdown of SigmaR1 or use of the ligand igmesine, which inhibits SigmaR1, abolished the SK3/Orai1 interplay of channels in cholesterol-rich nanodomains in breast and colon cancer cells." (PMID 35327543, 2022).
fibrosis (2 papers, 2021 to 2023). the formation of excess fibrous connective tissue in an organ or tissue in a reparative or reactive process. "In previous studies, we reported that Sigmar1 global knockout mice (Sigmar1−/−) developed cardiac contractile dysfunction, cardiac fibrosis, and mitochondrial respiratory defects." (PMID 37051024, 2023).